INS (insulin)
Diseases named in the same sentence as INS in open-access papers (continued):
Sharing a sentence is not in itself a finding about the gene and the disease.
Insulin resistance (continued). "According to case studies and randomized trials, therapeutic fasting has been shown to reverse insulin resistance, resulting in the discontinuance of insulin therapy while maintaining blood sugar levels." (PMID 34909309, 2021). "Previous studies have shown that ADMSCs promoted the body’s sensitivity to insulin and improve the body’s insulin resistance, MLT promote the effect of ADMSCs." (PMID 34722505, 2021). "TCF7L2 SNPs are strongly associated with various aspects of type 2 diabetes, including insulin resistance, impaired insulin secretion, altered insulin processing, diminished suppression of glucagon by glucose, and increased fasting hepatic glucose release." (PMID 33828529, 2021). "IGFBP1 is strongly regulated by insulin and decreased in subjects with insulin resistance and was inversely correlated with insulin levels, waist circumference and abdominal fat content in this study." (PMID 33686453, 2021). "Insulin resistance can be defined as a subnormal biological response to normal insulin concentrations." (PMID 34440963, 2021). "Because insulin resistance is a central trait of type 2 DM, oleanolic acid therapy increased insulin sensitivity by boosting the expression of insulin receptor and glucose transporter proteins in HepG2 cells." (PMID 34885816, 2021). "TBI-treated mice exhibit reduced proliferative and adipogenic capacity in SAT and develop systemic insulin resistance on high-fat diets, accompanied by decreased insulin responsiveness of preadipocytes isolated from VAT." (PMID 34554929, 2021). "Given such a variety of functions of insulin in the brain, the development of brain insulin resistance can lead to numerous pathological manifestations, especially to those associated with synapse failure and energy metabolism." (PMID 33810179, 2021). "Under insulin resistance, the insulin signaling in myocardial tissue is altered with impaired Akt and FOXO1 function." (PMID 33672590, 2021). "Unfortunately, side effects, including acute hypoglycemia and insulin resistance, are frequently observed in patients with long-term injected insulin treatment, which has driven research into adjunctive agent use in insulin therapy." (PMID 34955862, 2021). "Regarding its actions to increase insulin sensitivity, PPARγ agonists can also counteract the effects of insulin resistance on blood pressure." (PMID 34966295, 2021). "We also analyzed the changes in proteins related to insulin resistance, resulting in the inhibition of insulin signaling." (PMID 33968046, 2021). "The HOMA-IR (Homeostatic Model Assessment for Insulin Resistance, derived from fasting insulin and glucose) approximates insulin resistance in humans." (PMID 34206322, 2021). "Insulin resistance is the inability of exogenous or endogenous insulin to increase glucose uptake and use, basically the cells stop responding to the hormone." (PMID 33673200, 2021). "Insulin resistance is primarily due to downregulation or inactivation of insulin signaling, which is mainly mediated by insulin receptor substrates (IRSs) in effector organs." (PMID 34966295, 2021). "Early phases of insulin resistance development in skeletal muscle include extracellular matrix remodeling with increased physical barriers for insulin and glucose transport and decreased vascular insulin delivery." (PMID 34959870, 2021). "Because adiponectin favors insulin sensitivity, its low production is relevant to the insulin resistance of the CGL." (PMID 33411809, 2021). "Free fatty acids induce insulin resistance and inflammation in insulin-targeted organs, indicating a major link between obesity, insulin resistance, inflammation, and T2DM development." (PMID 34680529, 2021). "Though, the HOMA-IR, which assesses insulin resistance from fasting glucose and insulin levels, was significantly higher in DUSP3-KO compared to WT mice under both CD and HFD and all time points analyzed." (PMID 33712680, 2021).
Insulin resistance (continued). "The idea that EV can be also involved in obesity-associated comorbidities is supported by homeostatic model assessment for insulin resistance and by the positive correlation between MP number and the augmented fasting insulin level." (PMID 33477341, 2021). "In the study conducted by Juturu (2006), the serum insulin levels and insulin resistance had a significant correlation with HEI scores in the patients with type 2 diabetes." (PMID 33747570, 2021). "Type-2 diabetes (T2D) results from insulin resistance or insulin insensitivity and the regulation of the BG levels require oral medications or insulin." (PMID 34934084, 2021). "Type 2 diabetes (T2D) clinically manifests with the appearance of insulin resistance in insulin‐responsive target cells, progressively accompanied by compromised function of insulin‐producing pancreatic β cells in Langerhans islets." (PMID 34459017, 2021). "Danhong injection treatment ameliorated HFD-induced AS and insulin resistance by activating the PI3K/AKT insulin pathway induced by insulin receptor substance-1 (IRS-1)." (PMID 34873408, 2021). "In the case of T2DM or insulin resistance, the failure of insulin-dependent glucose uptake into fat and muscle tissues results in increased blood glucose concentrations and increased glucose uptake into insulin-independent tissues." (PMID 34945650, 2021). "Early, intermediate, and end glycation products as sources of oxidative stress and inflammation contribute to reduction of insulin secretion, insulin resistance, and vascular complications." (PMID 33995940, 2021). "Following LPS treatment, fasting glucose levels tended to be reduced, while the fasting insulin level and insulin resistance index (HOMA-IR) were significantly elevated." (PMID 34682732, 2021). "Chronic metformin treatment significantly reduced insulin levels (–63%, p <0.001), thereby preventing the development of insulin resistance." (PMID 34149616, 2021). "An increase in body fat leads to increased insulin resistance but soy isoflavones reduce body fat and thus decrease insulin secretion and prevent insulin resistance and pancreatic cell dysfunction by improving insulin sensitivity." (PMID 34209224, 2021). "Mice on O304-0.25 showed evidence of reduced insulin levels and reduced insulin resistance, i.e., HOMA-IR, already after 1 month of treatment compared with that at start and CD-fed mice." (PMID 34795407, 2021). "In type 2 diabetes, a decline in insulin action termed insulin resistance, followed by the inability of ß-cells to secrete enough insulin to compensate for the insulin resistance, is considered as the initial event leading to the developmental process of T2DM." (PMID 34899339, 2021). "Expression of adiponectin receptors has a close relationship with insulin resistance status and is inversely related to plasma insulin levels." (PMID 34094026, 2021). "This study addresses the effects of the androgen receptor and its blockade on plasma insulin and glucose as well as an index of insulin resistance." (PMID 33393733, 2021). "Insulin resistance is defined as impaired insulin signaling together with diminution in glucose transport, which promotes the development of diabetic cardiomyopathy." (PMID 34604360, 2021). "We evaluated insulin resistance by measuring the serum insulin level and homeostatic model assessment of insulin resistance (HOMA-IR)." (PMID 34135978, 2021). "In the case of pregnant women with insulin resistance, physicians usually suggest treatments with insulin sensitizers like metformin, even if contraindications exist." (PMID 34070701, 2021). "Insulin resistance has been defined as the decreased ability of insulin to stimulate glucose transport and metabolism in skeletal muscle and adipocytes." (PMID 33954196, 2021). "In fact, the physiological response to insulin resistance in the early stages of obesity is mainly attributed to an increase in pancreatic β-cell mass and insulin secretion." (PMID 34015524, 2021).
Insulin resistance (continued). "o-coumaric acid or coumarinic acid was found to restore glycemic control and insulin sensitivity in rats fed high fats/high sucrose diet and suffered from hyperglycemia and insulin resistance." (PMID 34335266, 2021). "In the present study, women showed lower whole-body and liver insulin resistance, with similar muscle insulin sensitivity compared to men." (PMID 34068687, 2021). "Normal β-cells can compensate for insulin resistance by increasing insulin secretion or β-cell mass, but insufficient compensation leads to the onset of T2DM." (PMID 34360682, 2021). "The main pathological status of patients with NAFLD is insulin resistance, Excessive insulin levels promote lipogenesis, leading to liver steatosis." (PMID 34220701, 2021). "The effects of Cr3 on healthy rats and rat models of insulin resistance and type 1 and type 2 diabetes have been examined where it was found to have beneficial effects on insulin sensitivity and, in most cases, lipid parameters." (PMID 32488613, 2021). "Various clinical studies from our hospital showed that high insulin resistance and high fasting plasma insulin levels can be found at an early age." (PMID 33708999, 2021). "In univariate linear regression analyses, all of these lipid species, with the exception of the LPI 20:4, are negatively associated with insulin resistance (HOMA-IR, fasting insulin) and, for the most part, also with BMI and CRP." (PMID 34684461, 2021). "Elevated oxidative stress and inflammation also induce insulin resistance: the inability of insulin-dependent cells to respond to insulin stimulation, which normally enhances the glucose uptake from the blood." (PMID 33922000, 2021). "One aspect of WAT dysfunction is WAT insulin resistance, which is partially characterized by insulin’s reduced ability to suppress lipolysis, resulting in higher rates of fatty acid delivery to liver and skeletal muscle." (PMID 33411692, 2021). "A preclinical study already suggested that the consumption of golden berry juice decreased blood glucose and insulin resistance and increased insulin levels in diabetic rats." (PMID 34579001, 2021). "To confirm that the high FPG observed in diabetic animals was due to insulin resistance, we performed an intraperitoneal glucose/insulin tolerance test at the end of the experimental period." (PMID 34202017, 2021). "Compared to the placebo, genistein significantly reduced the serum insulin levels (p = 0.001) and significantly improved insulin resistance (homeostasis model assessment of insulin resistance (HOMA-IR), p = 0.041)." (PMID 34641407, 2021). "On the basis of insulin resistance, obesity can increase the expression level of insulin and IGF, and promote the proliferation, invasion and metastasis of tumor cells." (PMID 34485124, 2021). "Insulin resistance indicates an inadequate strength of insulin signaling from the InsR downstream to the final substrates of insulin action involved in multiple metabolic and mitogenic aspects of cellular function." (PMID 33708999, 2021). "Adropin injection significantly reduced fasting blood glucose, inhibited hepatic glucose production, lowered fasting insulin level, and improved insulin resistance in high-fat diet mice." (PMID 34366886, 2021). "In fact, female NIRKO mice showed an increased food intake, and both male and female mice developed diet-sensitive obesity with increases in body fat and plasma leptin levels, mild insulin resistance, elevated plasma insulin levels, and hypertriglyceridemia." (PMID 34202916, 2021). "These mice exhibited marked insulin resistance, severe glucose intolerance, impaired glycogen storage, and a failure of insulin-induced suppression of hepatic glucose production." (PMID 33923817, 2021). "For example, subclinical hypothyroidism can result in insulin resistance due to a decreased rate of insulin-stimulated glucose transfer induced by a translocation of the GLUT 2 gene." (PMID 35106234, 2021).
Insulin resistance (continued). "As it has been mentioned in previous sections, decreased insulin secretion from the pancreatic islets and enhanced peripheral insulin resistance are observed in the course of PTDM." (PMID 33810367, 2021). "NR supplementation decreased levels of circulating inflammatory cytokines but did not produce favorable changes in body weight, blood pressure, lipid profile, fasting glucose and insulin, or homeostatic model assessment of insulin resistance (HOMA-IR)." (PMID 35173682, 2021). "AME ameliorated insulin resistance through blood glucose lowering effect and insulin signaling stimulation." (PMID 34679681, 2021). "The factors associated with irisin levels in acromegaly patients were insulin resistance indices (HOMA-IR, fasting insulin) and atherogenic factors (Castelli I Castelli II, AC)." (PMID 34795636, 2021). "Insulin resistance regulates insulin secretion, which ultimately leads to hyperinsulinemia, and hyperinsulinemia is associated with increased morbidity and mortality from cardiovascular complications in patients with obesity." (PMID 34203830, 2021). "Insulin resistance in T2DM is characterized by the inability in insulin response of the original insulin-sensitive tissues and reduced glucose uptake by the peripheral tissues." (PMID 34769364, 2021). "Abnormalities of insulin signaling transduction account for the impairment of insulin sensitivity and development of insulin resistance, which, in turn, is responsible for the enhancement of cardiovascular risk." (PMID 32737757, 2021). "Fasting plasma insulin and fasting insulin resistance measurements were significantly higher in patients with NAFLD, and more so in those with NASH." (PMID 34077443, 2021). "A study found that increased serum CRP and IL-6 levels correlated with elevated insulin levels and higher insulin resistance index (HOMA-IR) scores, further suggesting that inflammatory factors are closely related to IR." (PMID 33714202, 2021). "Obesity-induced insulin resistance results in a reduction in insulin-AKT phosphorylation while insulin-stimulated phosphorylation of AKT in eAT was slightly increased from RAGE−/−-HFD mice compared with RAGE−/−-ND mice (P > 0.05)." (PMID 34686659, 2021). "From 1814 detected studies, twenty-four studies reported fasting blood glucose (FBG), fasting insulin, hemoglobin A1C (HbA1C), and Homeostatic Model Assessment for Insulin Resistance (HOMA-IR) as an outcome measure." (PMID 34371867, 2021). "Bitter melon extract was also reported to improve the insulin sensitivity of skeletal muscle in high-fat-fed rats with signs of insulin resistance." (PMID 33746602, 2021). "Insulin resistance refers to a pathological condition of decreased insulin sensitivity of insulin-targeting cells and issues." (PMID 34108878, 2021). "Taken together, our data suggest that SARS-CoV-2 infection increases blood glucose and insulin levels, resulting in new-onset insulin resistance." (PMID 34916489, 2021). "True insulin resistance is usually marked by hyperinsulinemia and an increase in fasting insulin (with the exception of β-cell failure in type II diabetes) and coincides with sub-optimal metabolic heath." (PMID 33921683, 2021). "The similar loss of insulin sensitivity, as a marker of insulin resistance (IR), in HFD males and females is corroborated by their fasting plasma insulin levels, which were also similar and higher than their respective SD controls." (PMID 33692086, 2021). "Animal studies have shown that insulin resistance can impair osteoblastic insulin signaling and affect osteoblast proliferation and survival, and consequently block bone formation." (PMID 34202423, 2021). "In an experimental study, intranasal insulin administration induced insulin resistance, increased levels of catenin, collagen deposition, and bronchial hyperresponsiveness." (PMID 33520042, 2021).
Insulin resistance (continued). "It is important to note that the ratio of the concentration of insulin in cerebrospinal fluid compared to the periphery is lower in both aging patients with AD and those with insulin resistance compared to healthy subjects." (PMID 34497507, 2021). "Insulin resistance in insulin-sensitive tissues such as the liver, muscle, and adipose tissue and dysfunction of pancreatic β-cells can contribute to the development of hyperglycemia, hyperinsulinemia, insulin resistance, and T2DM." (PMID 33488888, 2021). "In murine models, the loss of autophagy generates an impairment in glucose-induced insulin secretion; a decreased in β cell mass and hyperglycemia in pancreatic β cells, as well as an increase in both ER stress and insulin resistance, in the liver." (PMID 34069890, 2021). "In rats, we have recently demonstrated that mid-gestational exposure to DHT and insulin (INS) produces a PCOS-like phenotype (i.e., hyperandrogenism and insulin resistance) with increased fetal loss." (PMID 34180022, 2021). "“Insulin resistance” is usually defined in terms of attenuated ability of insulin to stimulate glucose uptake." (PMID 33901270, 2021). "This resulted in PCA Dimension 1, mainly composed of glucose tolerance indicators, such as fasting insulin, insulin sensitivity, and insulin resistance, as well as beta cell function derived from the HOMA2 model." (PMID 33673242, 2021). "In people suffering from metabolic syndrome with the appearance of insulin resistance, these processes become weaker and weaker, so higher insulin concentrations are then required for the same effect." (PMID 33401397, 2021). "T2DM develops in association with insufficient insulin action related to decreased insulin secretion or insulin dysfunction through insulin resistance, which involves multiple genetic factors." (PMID 34769575, 2021). "Sex differences in insulin resistance, insulin secretion, glucose effectiveness or endogenous glucose production have already been shown in specific populations." (PMID 33475909, 2021). "In states of insulin resistance and peripheral hyperinsulinemia, insulin transport is reduced because of the saturation of insulin receptors in the blood brain barrier." (PMID 34502154, 2021). "Obesity often leads to systemic “insulin resistance” a phenomenon that is characterized by reduced insulin signaling in peripheral tissues resulting in several metabolic abnormalities." (PMID 33390183, 2021). "In adulthood, this cohort displays impaired glucose tolerance and insulin resistance possibly related to inadequate insulin secretion or action." (PMID 34828683, 2021). "In wild-type mice exposed to iAs and fed a high-fat diet with low folate dose, adverse effects on glucose homeostasis (marginal increase in fasting plasma insulin levels and homeostasis model assessment of insulin resistance) were observed." (PMID 34678954, 2021). "Mechanistically, FAF1 interacts directly with c-Jun N-terminal kinase (JNK) and activates its phosphorylation, thereby blocking the downstream insulin signaling pathway and leading to insulin resistance." (PMID 33510836, 2021). "It is believed that endocrine and metabolic diseases characterized by elevated blood glucose due to insulin resistance and death of insulin-producing pancreatic islet β-cells can lead to chronic cardiovascular diseases and ultimately to AD." (PMID 34824300, 2021). "Inflammatory cytokines and other factors can interfere with the normal insulin signaling pathway and activate the insulin resistance signaling pathway, leading to insulin resistance and T2DM." (PMID 34335798, 2021). "Female D1KO mice also displayed insulin resistance on the regular chow diet, as shown by increased fasting and fed insulin levels and impaired glucose tolerance and insulin sensitivity in GTT and ITT tests." (PMID 34824202, 2021).